CD34 (CD34 molecule)
Diseases named in the same sentence as CD34 in open-access papers (continued):
Sharing a sentence is not in itself a finding about the gene and the disease.
cancer (418 papers, 1997 to 2026). A tumor composed of atypical neoplastic, often pleomorphic cells that invade other tissues. "For instance, biomarkers such as EZH2 (high-risk) and CD34 (protective) would benefit from validation against GTEx-derived normal cervical tissue expression to confirm their cancer-specific dysregulation." (PMID 40678068, 2025). "EphA2 has been shown to regulate VE-cadherin-mediated signalling and matrix degradation, while CD34 expression has been linked to endothelial-like phenotypes in aggressive cancers." (PMID 41228228, 2025). "Subcluster MTC0 was characterised by high expression of TSPAN8 (encoding tetraspanin 8), which is overexpressed in many cancers, and CD34, a common marker for diverse progenitors." (PMID 38318640, 2024). "It is worth noting that in cancer patients, defects in immune cell maturation and increased levels of immature forms of myeloid suppressor cells or CD34+ progenitor cells were also associated with lower vitamin D3 levels." (PMID 37299554, 2023). "Conversely, high CD34 expression is associated with poor therapy response and an altered gene expression profile resembling that of migrating cancer stem-like cells." (PMID 38250553, 2023). "Vimentin, fibroblast-associated protein (FAP), CD34, and alpha smooth muscle actin (αSMA) are the most frequently utilized markers for evaluating cancer-associated fibroblasts (CAFs)." (PMID 37568639, 2023). "During these processes, proliferating CD34+SCs/TCs lose CD34 expression and gain αSMA expression, differentiating into myofibroblasts (cancer-associated fibroblasts, CAF, in tumors)." (PMID 36012273, 2022). "In sprouting angiogenesis, proliferating perivascular CD34+SCs/TCs are an important source of stromal cells during repair through granulation tissue formation and of cancer-associated fibroblasts (CAFs) in tumors." (PMID 36012273, 2022). "Given the existing knowledge of CD34 in cancer cells, we investigated our dataset for possible associations between CD34 expression and stemness, migration, adhesion, and survival hoping to gain insight into the causes of the generalized variation." (PMID 35271751, 2022). "No studies to date have reported an increased risk of uncontrolled cell growth of CD34+ inoculated tissues, angiomas or cancer." (PMID 34066713, 2021). "Several origins have been proposed for cancer-associated fibroblasts (CAFs), including resident CD34+ stromal cells/telocytes (CD34+SCs/TCs)." (PMID 33916213, 2021). "In the CD34+ group, five deaths were due to cardiovascular disease, two deaths were due to cancer, and cause of death was unavailable for two subjects." (PMID 32531108, 2020). "We chose two types of infiltrating malignant epithelial neoplasms in adipose tissue as examples of the different behaviour of tissue resident TCs/CD34+SCs: with the conservation or loss of CD34 expression, and with the gain of αSMA expression." (PMID 33353193, 2020). "A report showed CD34+ subpopulation in K562 cells was much less sensitive to IM than the bulk, which supported that cancer stem cells are the mainly cause of drug resistance." (PMID 27027438, 2016). "Since low p27 cellular levels have been associated with response to plitidepsin in several cancer cells, we measured the levels of p27 mRNA in CD34+ cells from PMF patients compared with controls." (PMID 25768401, 2015). "In malignant tumors it was noticed a loss of CD34 positive cells and gain of smooth muscle cell actin positive myofibroblasts and this is in keeping with our findings." (PMID 22067528, 2011). "Interestingly, we observed a major population of CD34– cancer-associated fibroblasts (CAFs) in raGFP-Wnt1 tumors that was not apparent at the hyperplastic stage (MGhyper)." (PMID 40216939, 2025).
cancer (continued). "Moreover, we found that cancer‐associated CD45+ EPCs induced the death of CD34+ cells, which are considered thymocyte cell seeds." (PMID 40665793, 2025). "Additionally, the MFI of the cancer stemness marker CD24 was significantly associated with the percentage of GSHlo MITOhi CD34+ cells, suggesting a mirrored effect of cell metabolic status on EV surface expression markers." (PMID 39738118, 2024). "When HCC patient tissues were cultured on the oxygen gradient chip for 4 days, typical HCC showed increased expression of protein markers associated with hypoxia-mediated stemness (CAIX), cancer invasiveness (K19), and microvascular invasion (CD34) on the normoxic side compared to the hypoxic side." (PMID 38879551, 2024). "Therefore, as well as for regenerative stem cells, in the case of CD34 expression on cancer cells and CSCs, CD34 was linked with endothelial progenitors and adult cells and angiogenesis." (PMID 37241170, 2023). "Based on all these previous data, we hypothesized that the impact of CD34- and αSMA-positive cancer-associated fibroblasts (CAFs) may be distinct for each subtype and may be accurately enhanced by using DIA associated with immunohistochemistry interpretation." (PMID 37568639, 2023). "Therefore, the fact that there is a positive association between height and cancer can also be explained by this mechanism: height determines the level of CD34-positive cell production." (PMID 33549053, 2021). "Nearly all families were also DHS-enriched in CD34+ cells, suggesting an association with a stem-cell state, which may be exploited by cancer cells to promote cell proliferation and survival." (PMID 32665538, 2020). "However, the mechanism leading to the loss of CD34 fibrocytes in the stroma of carcinomas are far from being understood." (PMID 23469238, 2013). "In addition, a remarkably positive correlation was observed between miR-30a-5p and CD31, and between miR-30a-5p and CD34, suggesting that miR-30a-5p might be involved in cancer-associated angiogenesis." (PMID 37781039, 2023). "Consequently, the loss of CD34+ fibroblasts accompanies the precancer-to-cancer transition." (PMID 37190121, 2023). "Merck’s angiogenic signature was selected as genes co-expressed with known angiogenic genes, KDR, TIE1, TEK, and CD34, in public pan-cancer genomic datasets." (PMID 39835481, 2025). "Here, we assessed if this immunological function of ALDH1A3 is preserved in human cancers by replicating this mechanistic approach in a human solid cancer model using CD34-humanized mice." (PMID 41210994, 2025). "Exploration of alternative methods for the collection of CD34+ cells from adult cancer patients remains worthy of investigation." (PMID 40508078, 2025). "Research indicates that the expression levels of general stem cell markers (such as CD34 and CD73), genes linked to cancer stem cells (CD99 and ITGB3), and an embryonic stem cell marker (GGT1) are elevated within this subset." (PMID 41204265, 2025). "We identified three major stromal cell types, including cancer-associated fibroblasts (CAFS; FAP, COL1A1), perivascular-like cells (PVL; PDGFRA, PDGFRB), and endothelial cells (PECAM1, CD34)." (PMID 40858992, 2025). "Cell–cell communication identified a stronger interaction between cancer.cell. and CAF_C3, as well as Fibrocyte_CD34, in post-NACT samples, indicating that chemotherapy reshapes pre-existing cell clusters in a site-dependent manner." (PMID 40725006, 2025). "For more than three decades, G-CSF has been the primary method for mobilizing HSCs in both allogeneic donors and cancer patients, increasing peripheral blood CD34 + cell concentrations by 10–20-fold." (PMID 41194247, 2025). "We tested the ability of Val-ILs to eradicate cancer cells when CD34+ hematopoietic stem cells (HSC) isolated from human cord blood were deliberately contaminated with ~1% of GFP+ B-ALL cells." (PMID 38734740, 2024).
cancer (continued). "We further tested the effectiveness of Val-ILs-αCD19 in eradicating cancer cells when CD34+ HSC were contaminated with GFP+ B-ALL cells and then transplanted into NSG mice." (PMID 38734740, 2024). "Those generated in vitro from Lin-CD34+DNAM-1bright cells purified from cancer tissue displayed significantly greater cytotoxicity compared to those derived from tissue Lin-CD56-CD16+ cells and from peripheral blood (PB)." (PMID 38390333, 2024). "Analysis of DNAM-1 MFI in CD34+DNAM-1brightCXCR4+ cells showed a higher mean DNAM-1 density in peripheral blood vs. cancer-tissue precursors (p=0.03)." (PMID 38390333, 2024). "The current challenge in the field of stem cell research and therapy is the potential implications of CD34 markers in cancer pathology." (PMID 37241170, 2023). "Lack of an endothelial cell lining is confirmed by IHC using labelling for CD31 or CD34 in VM studies across various cancer types." (PMID 36823554, 2023). "Human peripheral blood mononuclear cells (PBMCs) are more readily available from cancer patients than CD34+ HSPCs." (PMID 37296949, 2023). "In this paper, we aimed to carry out a systematic analysis of the structure, functions, and relationship with the cancer stem cells of CD34 based on the literature overview." (PMID 37241170, 2023). "The limited availability of CD34+ cells from cancer patients, together with the significantly lower immune cell reconstitution capacity of adult CD34+ cells, represents a major obstacle to the generation of PDX mice with an autologous human immune system." (PMID 37296949, 2023). "In this paper, we aimed to carry out a systematic analysis of the structure, functions, and relationship with cancer stem cells of CD34 based on the literature overview." (PMID 37241170, 2023). "Based on information available in the literature, CD34 has been identified in various cancers, such as gastric, breast, thyroid, colorectal, and skin cancer." (PMID 37241170, 2023). "We further demonstrated that VISTA antibody on IgG4-Pro backbone increased the interaction of effector immune cells with CD34+ AML cancer cells in ex vivo patient samples; that effect was similarly reduced by an IgG1-KO backbone." (PMID 35967294, 2022). "CD34 is a cell surface sialomucin-like adhesion molecule and its expression is considered as a convenient marker of cancer stem cells (CSCs) and hematopoietic stem cells (HSCs), which maintain self-renewal and differentiation capacity." (PMID 36500358, 2022). "The cancer cells show high proliferative activity, and the stromal cells are CD34-positive stromal cells, suggesting the immaturity of the interstitial tissue." (PMID 35054150, 2022). "In this primary model, CD3+ cells within samples stimulated with J014-IgG4-Pro increased their interactions to CD34+ AML cancer cells, and simultaneously an increase of surface CD107a expression was observed suggesting T cell activity." (PMID 35967294, 2022). "Metastasis will become established upon cancer cell proliferation with angiogenesis induced by CD34-positive stromal cells." (PMID 35054150, 2022). "When we added VISTA antibody on IgG4-Pro backbone to ex vivo AML patient samples, we observed an increase in the interaction of T cells with CD34+ AML cancer cells." (PMID 35967294, 2022). "For example, the use of electroporation to directly deliver CRISPR material to CD4+ T cells, CD34+ stem cells, cancer cells and embryonic stem cells has been shown." (PMID 34188916, 2021). "For example, an increase of Wnt-producing CD34+ cells forming the stem cell niche has been proposed to promote inflammation-induced cancer." (PMID 34849464, 2021). "Progression of cancer requires angiogenesis, and CD34-positive cells play an important role in this process." (PMID 33549053, 2021). "TCL1A is crucial for cancer development by expressing in a subpopulation of immune B cells (CD3-/CD19+/CD10+/CD34-)." (PMID 33833937, 2021).
cancer (continued). "CD34 is one such marker, and is used not only for glioblastomas, but also for other subtypes of cancer (liver, pancreas, leukemia..)." (PMID 34638987, 2021). "To validate the zebrafish as a potential in vivo pre-clinical model, we xenotransplanted different human cells, including cancer cells and normal human primary cells (CD34+ HSPC and CD3+ T-cells)." (PMID 33707624, 2021). "They express cancer stem cell markers, such as CD34, MMP2, nestin, and SOX2, as well as the astro-neuronal lineage markers GALC, TUBB3 (CD56), and OLIG2." (PMID 34638987, 2021). "Subsequently, we also observed that CD34-overexpressing PKP+ cancer cells increased p-AKT, p-STAT3, and CD44 cancer stemness protein expression, but reduced p-AMPK protein levels according to Western blot analysis." (PMID 32586050, 2020). "The appearance of CD34-positive endothelial cells plays a vital role in understanding the process of angiogenesis in oral cancer and pre-cancer." (PMID 33383808, 2020). "Overall, plerixafor was generally well tolerated and efficacious when used to mobilize CD34+ cells in pediatric patients with a variety of different cancers." (PMID 32127657, 2020). "We demonstrated that NK cells differentiated from CD34+ cells isolated from cord blood show increased antitumor potential in vitro against different cancer cells." (PMID 32592353, 2020). "These MPs differ phenotypically in the expression of four protein biomarkers: a plasma-cell marker (CD138), the MDR protein, P-glycoprotein (P-gp), the stem-cell marker (CD34); and phosphatidylserine (PS), an MP marker and mediator of cancer spread." (PMID 32170169, 2020). "Instead, they express constellation of group-defining genes, including Ly6a, Cd34, and Thy1, which have been shown to mark other adult stem cells, such as HSCs, keratinocyte stem cells, cancer stem cells, muscle stem cells etc." (PMID 32286228, 2020). "The understanding of the angiogenic process in malignant tumors strongly depends on finding the CD34 marker in blood vessel endothelium." (PMID 33383808, 2020). "Plerixafor + standard G-CSF ± chemotherapy mobilization was generally well tolerated and efficacious when used to mobilize CD34+ cells in pediatric cancer patients." (PMID 32127657, 2020). "Overall, we want to point out that we don't know the origin of this cell population or if these cells are indeed disseminated cancer cells or even a group of haematopoietic progenitor CD34 + stem cells." (PMID 32021935, 2020). "Recent work by the authors showed elevated ALP activity in CD34+ cells in highly refractory cancers." (PMID 31857851, 2019). "CD133 is documented as a more specific marker of hematopoietic stem cells than CD34, and a marker of cancer stem cells (CSC) discovered in many tumors." (PMID 31807115, 2019). "The most obvious distinction between our results and those of previous studies is the involvement of CD31/CD34-positive cancer cells in the formation of VM channels." (PMID 30833656, 2019). "Several genes were found to be up-regulated including Nos2, PLAT, and CD34 many of which are involved in Wnt/β catenin signaling, a pathway known to drive cell proliferation and regulate cell-cell adhesion in cancer 29–32." (PMID 31796785, 2019). "The data present in this study showed elevated expressions of β-catenin and CD34 in A2780-M, suggesting that A2780-M cells are with phenotype of cancer stem cells (CSCs)." (PMID 30046596, 2018). "Our results also revealed that A2780-M cells express increased levels of cancer stem cell surface markers such as β-catenin, CD34, CD133, and CD44." (PMID 30046596, 2018). "The Mann–Whitney test demonstrated significantly lower MVD/CD34 ratios among patients with T3–T4 tumors compared to those with T1–T2 cancers (U = 442 for p = 0.01)." (PMID 29748768, 2018).
cancer (continued). "We found that differentially methylated CpG sites located to genes involved in ‘cancer’ and ‘embryonic development’ in MF CD34+ cells, in ‘inflammatory disease’ in MF mononuclear cells, and in ‘immunological diseases’ in MF granulocytes." (PMID 28754985, 2017). "In our present study, DMBA-induced CD34+ and Lgr6+ cancer stem cells were characterized by extensive telomere shortening despite ALT activation." (PMID 29113290, 2017). "s4428z- or truncated CD34-transduced T-cells were cocultured overnight with several cancer cell lines and were analyzed for surface expression of the activation marker 4-1BB (CD137)." (PMID 29085357, 2017). "TRF2 null SCC exhibited marked expansion of CD34+ cancer stem cells as previously reported (37; 8.0%; P < 0.003)." (PMID 29113290, 2017). "As previously reported, LY2510924 peptide administered over a range of 1- to 30-mg/day dosing had a favorable pharmacokinetic profile and induced dose-dependent increases in neutrophils and CD34+ HSCs in patients with advanced cancer." (PMID 29212254, 2017). "Despite their significant depletion, CD34+ and Lgr6+ cancer stem cells were tumorigenic following transplantation." (PMID 29113290, 2017). "At this time, interestingly, albeit the cancer cell-induced decrease, CD34 expression was always higher than that expressed by hASCs cultured alone; furthermore, Saos2 cells led to a greater increase in CD34 expression when compared to the MCF7 cells." (PMID 28102844, 2017). "These integrin αv expressing cells represented a distinct population from other cancer stem cell populations, including significantly reduced CD34 and Lgr6 expression and failure to give rise to these known cancer stem cell populations." (PMID 29113290, 2017). "Gene expression analysis of the CD34-Lgr6- cancer cell population revealed 7 fold increased expression of integrin αV (Itgav; P < 0.02)." (PMID 29113290, 2017). "In phase I dose-escalation and dose-confirmation studies of both agents in patient with advanced cancer, circulating WBCs, neutrophils, and CD34+ HSCs were evaluated as clinical biomarkers." (PMID 29212254, 2017). "Both CD34+ and Lgr6+ cancer stem cell populations from K14Cre;TRF2f/f;Terc-/- SCCs were tumorigenic in our transplantation experiments." (PMID 29113290, 2017). "We have further shown that restoration of TGFβRII in Tgfbr2 cKO SCC reduced the frequency of these CD34+ CSCs, demonstrating that loss of TGFβ signaling is a requirement for CSC maintenance in transition zone carcinoma." (PMID 28219480, 2017). "For CD34+ cells, 15% of the top target genes scored as cancer drivers (enriched compared to total genome baseline, p = 2.69E-18), for K562 the number was 11% (p = 2E-9) and for HepG2 6% (p = 0.0096)." (PMID 27097319, 2016). "For this meta-analysis we used published insertion data from two human cancer cell lines, K562 and HepG2 and normal CD34+ cells." (PMID 27097319, 2016). "Cancer stem cells are believed to form vascular mimicry channels that express various markers including CD34, CD44, and CD133 as well as PAS+ staining." (PMID 27834402, 2016). "Large scale studies of MLV vector integration in human CD34 cells or MLV pseudotype infection of human cancer cell lines has revealed a remarkably selective process in which more than half of the integrations target less than 2% of the human genome." (PMID 27097319, 2016). "Regardless of the passage, ADSCs derived from normal breasts were CD34+, in contrast to CD34-negativity in cancer afflicted breast tissue-derived ADSCs." (PMID 26000019, 2015). "It is reported that the Notch signaling is important for the maintenance of self-renewal in human CD34+ cord blood cells and cancer-initiating cells as well." (PMID 25669984, 2015). "For example, Ki67 expression level in cell nuclei is often assessed to quantify proliferation of cancer cells, and CD34 staining is used for quantifying endothelial cells of micro-vessels in order to assess angiogenesis in tumors." (PMID 26013572, 2015).